IL5 (interleukin 5)
Diseases named in the same sentence as IL5 in open-access papers (continued):
Sharing a sentence is not in itself a finding about the gene and the disease.
Stroke (18 papers, 2011 to 2025). Sudden impairment of blood flow to a part of the brain due to occlusion or rupture of an artery to the brain. "Anti-IgE was associated with a lower risk of congestive heart failure, peripheral artery disease, and stroke, whereas anti-IL5/IL5R was associated with a lower risk of congestive heart failure, arrythmia, and peripheral artery disease." (PMID 40823190, 2025). "Anti-IgE was associated with a lower risk of congestive heart failure, peripheral artery disease, and stroke, whereas anti-IL5/IL5R therapy was associated with a lower risk of congestive heart failure, arrythmia, and peripheral artery disease compared with similar eligible non-biologic users." (PMID 40823190, 2025). "In contrast, patients who despite their therapy still experienced hospitalized exacerbations, had a higher risk of stroke associated with anti-IgE therapy and a higher risk of PAD associated with anti-IgE or anti-IL5 therapy." (PMID 40823190, 2025). "It has been revealed that IL-5 reduces the mortality rate of neurons after cerebral infarction, promotes neuronal regeneration and recovery, and regulates the post-stroke injury microenvironment." (PMID 38742047, 2024). "Studies have shown that serum levels of IL-6, IL-5, IL-10, and IL-2 in stroke patients are closely correlated with stroke prognosis." (PMID 38742047, 2024). "IL-5 has been discussed as a potential predictive factor for positive functional outcome after stroke." (PMID 38853210, 2024). "IL-5 plays beneficial roles in the repair of brain damage, suppresses post-stroke inflammation, and has a the capability to induce neurotrophic factors in astrocytes." (PMID 36330425, 2022). "IL-5 and IL-9 are decreased in severe stroke patients acute ischemic stroke patients with poor outcome than mild stroke." (PMID 35173738, 2022). "Th2 type cytokines including interleukin-4 (IL-4) and interleukin-5 (IL-5) were found to play beneficial roles in the repair of brain damage, suppress post-stroke inflammation, and have the capability to induce neurotrophic factors in astrocytes." (PMID 31164999, 2019). "IL-4 is mostly known as an anti-inflammatory cytokine and IL-5 have been shown to suppress post-stroke inflammation." (PMID 31164999, 2019). "In our study, we found that serum concentrations of IL-4, IL-5 and IL-9 were significantly elevated in minor stroke patients and negatively related to the NIHSS score." (PMID 31164999, 2019). "At one week following stroke GM-CSF, IL-1β, and IL-5 were reduced, and MIP-1α and MIP-1β were increased in the infarct of the OPN-/- mice." (PMID 30417081, 2018). "At 24 h following stroke, IL-5 and IL-6 were increased in the infarct of the OPN-/- mice compared to the WT mice." (PMID 30417081, 2018). "Il-4 (mostly regarded as anti-inflammatory cytokine) and IL-5 were found to play a beneficial role in brain repair, modulate microglial response, and suppress post-stroke inflammation." (PMID 27829437, 2016). "In C57BL/6 mice at 7 weeks post-stroke there were increased levels of G-CSF, GM-CSF, IFNγ, IL-1α, IL-5, IL-6, IL-12 (p40), IL-12 (p70), IP-10, KC, MCP-1, MIP-1α, MIP-1β, MIP-2A, RANTES, and TNFα within the infarct compared to the equivalent area of cortex from sham mice." (PMID 27600707, 2016). "More importantly, recent studies suggest that IL-5 expression in peripheral blood is reduced after stroke, which is independently associated with stroke severity and poor outcome; this suggests that reduced IL-5 may also be involved in the post-stroke reduction in eosinophil count." (PMID 38066457, 2023). "Additionally, compared to mild stroke patients, the IL-5 level is decreased in severe stroke patients with poor outcomes and may be used as a predictor of edema and infarct volume." (PMID 36552117, 2022). "In our study, the salivary concentration of IL-2, IL-5, IL-7, IL-10, IL-12 (p70), IL-13, IL-15, and IFN-α2 was below the detection level in healthy controls (most commonly) and in stroke patients." (PMID 40520895, 2025).
Stroke (continued). "Inflammatory response was determined by detecting levels of cytokines (interleukin-2 [IL-2], IL-4, IL-5, IL-8, IL-6, IL-10, IL-12p70, IL-17, tumor necrosis factor-α [TNF-α], interferon-γ [IFN-γ], IFN-α, and IL-1β) within 14 days after stroke onset." (PMID 38902691, 2024). "After stroke, males displayed greater mortality, worse sensory-motor deficit, and higher serum levels of proinflammatory cytokines IL-17A, MCP-1, and IL-5 as compared to females." (PMID 33451354, 2021). "The intersection of the top 10 genes from the two stroke outcomes are seven genes with T2DM, these include CCR4, IFNA2, IL-9, IL-7, IL-5, CCR3, and IL-27." (PMID 32010048, 2019). "The seven important predictor genes (CCR4, IFNA2, IL-9, IL-7, IL-5, CCR3, and IL-27) that overlapped both stroke outcomes had mean fold change ranging from 3.98 to 35.06." (PMID 32010048, 2019). "However, it must be noted that in a severe, permanent carotid artery occlusion model of stroke, simultaneous deletion of IL-13, IL-9, IL-4, and IL-5 did not worsen the neurological outcome." (PMID 36639371, 2023).
psoriasis (17 papers, 2014 to 2025). An autoimmune condition characterized by red, well-delineated plaques with silvery scales that are usually on the extensor surfaces and scalp. "AD is classically associated with dysregulation of the Th2 subset (IL-4, IL-5, IL-13, and IL-31), whereas the Th17 subset (IL-17, IL-21, and IL-22) has been implicated in the pathogenesis of psoriasis." (PMID 40535962, 2025). "Exceptions included genes located at the MHC locus showing a potential increase in risk of ulcerative colitis and multiple sclerosis, and at the IL5/IL13 locus showing a potential increase in risk of psoriasis." (PMID 34103634, 2021). "In the case of the psoriasis model, a TH17-associated cytokine cocktail (IL-17A and IL-22) was used, and in the case of the AD model, a TH2-associated cytokine cocktail (IL-4, IL-5 and IL-13) was used." (PMID 38251799, 2024). "In AD, the predominant cytokines are IL-4, IL-5, and IL-13, and the pathogenesis differs from that of psoriasis." (PMID 39519167, 2024). "Eosinophils are involved in type II immune response, which is related to T helper 2 cells and various interleukins (including IL-4, IL-5, IL-9, IL-13, IL-31, and IL-33, among others), differing from the IL-17/23 axis of psoriasis." (PMID 36865550, 2023). "Nevertheless, several studies also observed a significant increase in eosinophils and cytokines, such as IL-4, IL-5, IL-9, IL-31, and IL-33, among others, in the blood of patients with psoriasis." (PMID 36865550, 2023). "IL-ra expression was elevated in peripheral blood mononuclear cells of psoriasis patients compared with controls, while serum IL-5 levels were significantly elevated in psoriatic patients and were significantly overexpressed during the active phase of psoriasis vulgaris." (PMID 35769988, 2022). "In psoriasis, the absence of Th2-defining cytokines [interleukin (IL)-4, IL-5, and IL-10] and the increased presence of Th1 cytokines (interferon gamma (IFN-γ), tumor necrosis factor (TNF) and IL-12) prompted researchers to classify psoriasis as a Th1-mediated disease." (PMID 31019502, 2019).
Hepatic fibrosis (15 papers, 2013 to 2025). The presence of excessive fibrous connective tissue in the liver. "IL-5 signaling in the liver has been implicated in liver fibrosis, a common finding with AFB1 exposure effects." (PMID 40793786, 2025). "In a group of patients with advanced liver fibrosis, liver steatosis was linked with lower serum concentrations of IL-4, IL-5, IL-9, IL-10, IL-13 and IL-22." (PMID 39200991, 2024). "Given that previous findings have associated Th2 responses with enhanced hepatic fibrosis, the significantly elevated Th2 cytokines IL-4 and IL-5 in co-infected patients may be a major reason that co-infected patients tend to have accelerated progression of HCV." (PMID 23593207, 2013). "IL-33 induces M2-type polarization in macrophages and the release of IL-5 and IL-13 to promote liver fibrosis." (PMID 38105713, 2024). "In a subgroup of patients with advanced liver fibrosis, SLD was linked with lower serum concentrations of IL-4, IL-5, IL-9, IL-10, IL-13 and IL-22 and higher concentrations of HGH and VEGF." (PMID 39200991, 2024). "In the liver fibrosis, the increased levels of IL5 lead to progress of tissue damage by regulating IL13 production and macrophage activation." (PMID 28288584, 2017). "Th2 cytokines IL-4, IL-5 and IL-13 are dramatically increased in liver fibrosis with IL-13 being an indispensable mediator of fibrosis." (PMID 26771187, 2016). "Additionally, IL-5 knockout is able to reduce hepatic fibrosis in S. mansoni-infected mice." (PMID 33692784, 2021). "The study demonstrated that IL-5 stimulated the Th2 lymphocyte response and indirectly upregulated IL-13, shown to be a key mediator in the development of fibrosis, indicating IL-5 could have both a direct and an indirect effect on eosinophil mediated liver fibrosis." (PMID 34737752, 2021).
inflammatory bowel disease (15 papers, 2016 to 2025). A spectrum of small and large bowel inflammatory diseases of unknown etiology. "Earlier studies identified SNPs in the region of the IL5 and IL5a genes as being associated with inflammatory bowel disease (rs2188962), eosinophil count (rs4143832) and coronary artery disease (rs2706399)." (PMID 26821299, 2016). "Specifically, inulin supplementation elevates bile acid levels produced by gut microbiota, which in turn activates immune cells to produce the inflammatory cytokine IL‐5, thereby contributing to intestinal inflammation and worsening inflammatory bowel disease." (PMID 40027480, 2025).
lung disease (15 papers, 2013 to 2025). "Th2 cells mainly produce interleukins (IL)-4, IL-5, and IL-13, which promote eosinophil recruitment and contribute to the development of Th2-associated lung disease." (PMID 40026847, 2025). "Both IL-5 and IL-13 have assumed to be related to pathological responses, and have been linked to the development of lung diseases." (PMID 29107999, 2017). "In addition to an increased IL-17 response to the lysate in CF/ABPA/CPA patients (median, 14.3 versus 1.3 pg/mL in controls), significantly greater induction of the Th2 cytokines IL-4 and IL-5 was found in samples from patients with Aspergillus-associated lung diseases." (PMID 34201183, 2021). "In pulmonary diseases, systemic inflammation and increased TNF-α and interleukin-5 (IL-5) cause hyperglycemia with impaired skeletal muscle glucose absorption." (PMID 37187644, 2023). "Among these, IL-5, IL-17, IL-13, IL-23, and IL-6 are pro-inflammatory cytokines upregulated in patients with pulmonary diseases." (PMID 35806353, 2022). "The CD8+ T cells inhibit IL-5 synthesis to reduce the eosinophil infiltration in models of experimental lung disease." (PMID 36014805, 2022). "Moreover, NLRP3-derived cytokines (e.g., IL-1β, IL-18) appear to be the main inducers of a cytokine cascade (involving IL-23, IL-17, IL-26, IL-6, IL-13, and IL-5) that is responsible for the development of pulmonary diseases in morbidly obese subjects." (PMID 35806353, 2022). "Considering the role of eosinophils in organ injury, it is possible to suppose that treatment with anti-IL-5/IL-5R mAbs might allow us to improve, or prevent, not only lung disease but also extra-pulmonary involvement." (PMID 36359208, 2022). "Compared with traditional biomarkers such as IL-5, TSLP, and TARC, microbiota biomarkers also represent a vital role in the development and progress of lung diseases." (PMID 34621687, 2021). "In the pathogenesis of bleomycin-induced lung disease, transforming growth factor-β (TGF-β), tumor necrosis factor-α (TNF-α), IL-1, IL-5, IL-6, platelet-derived growth factor (PDGF) and a variety of cytokines such as chemokines play important roles." (PMID 23558450, 2013). "While deficiency in IL-33 signaling attenuated infection-induced ILC2 numbers and their production of IL-13 and IL-5 in these studies, it remained unclear, whether ILC2s and their cytokine production significantly contributed to AAM differentiation and the severity of pulmonary disease." (PMID 32117319, 2020).
periodontitis (14 papers, 2014 to 2026). An acute or chronic inflammatory process that affects the tissues that surround and support the teeth. "Our data has shown that periodontitis group (P) per se caused an increase in the total number of cells, mainly in the eosinophils and lymphocytes, as well as in the IL-5 cytokine release and mucus production." (PMID 29145431, 2017). "IL-5 is a cytokine involved in the activation and recruitment of eosinophils, which contribute to inflammation and tissue damage in periodontitis." (PMID 38891939, 2024). "We evaluated the effects of ω-3 PUFA on the cytokines TNFα, IL-2, IFNγ, IL-4, and IL-5 in a P. gingivalis ligature-induced periodontitis in the serum of mice." (PMID 37378834, 2024). "Intriguingly, similar cytokines play a role in periodontal disease and the inflammatory mucous membranes of airways.Both IL-5 and IL-6 were found to be increased in asthmatic patients and those suffering from periodontitis." (PMID 38352910, 2024). "The application of EV therapy in periodontitis presents significant clinical opportunities by demonstrating how EVs can influence key cytokines like IL-5, IL-6, IL-17A, IL-10, and TNF-α." (PMID 38891939, 2024). "Subsequently, we showed that human periodontitis is associated with increases in each ILCs subtype with the effect more marked for ILC2s and that mRNA expressions for IL-33 and IL-5 are markedly greater for sites affected by periodontitis than healthy sites." (PMID 28861078, 2017). "In light of the more marked expansion of the pool of ILC2s in periodontitis, we also explored mRNA expression of ILC2s-related cytokines, namely IL-5 and IL-13; we also determined expression of IL-33 since it is a pivotal regulator of function of ILC2s." (PMID 28861078, 2017). "Induction of periodontitis in wild mice markedly increased expression of IL-33 but expression levels of IL-5 and IL-13 resembling those of sham-operated groups." (PMID 28861078, 2017). "CD8 + T cell clones, which can originate from periodontitis-affected tissues, may secrete cytokines like IL-4 and IL-5 to inhibit the production of IFN-γ and promote humoral immune responses." (PMID 39014403, 2024). "We also observed that six molecules (IL-4, IL-5, IL-12, IL-13, IL-21, and IL-23) were intimately related in the periodontitis sites of all evaluated groups, regardless of risk factors." (PMID 37835794, 2023). "Interestingly, however, induction of periodontitis in AMPK KO mice further increased IL-33 mRNA expression and also caused significant increases in expression levels of both IL-5 and IL-13." (PMID 28861078, 2017). "In patients with periodontitis, the present study observed increased levels of pro-inflammatory factors IFN-γ, IL-1β, IL-2, IL-7, IL-21, and TNF-α, in addition to decreased levels of anti-inflammatory factors IL-5 in GCF of T2DM patients." (PMID 33417619, 2021). "In patients with periodontitis, lower levels of pro-inflammatory factors IFN-γ, IL-1β, IL-2, IL-6, IL-7, IL-21, TNF-αand higher levels of anti-inflammatory factors IL-4 and IL-5 in gingival crevicular fluid in the Sp group were identified than those in the Dp group." (PMID 33417619, 2021). "Nonetheless, it is intriguing that IL-33, but not IL-5 or IL-13, is increased in the WT/periodontitis group but knockdown of AMPK “unleashes” expression of ILCs-2-related cytokines." (PMID 28861078, 2017). "As found in the present study, in T2DM patients with periodontitis, statins treatment reduced pro-inflammatory factors IFN-γ, IL-1β, IL-2, IL-6, IL-7, IL-21 and TNF-α levels in GCF, and enhanced anti-inflammatory factors IL-4 and IL-5 levels through the anti-inflammation and anti-oxidation effects." (PMID 33417619, 2021). "Importantly, however, upregulation of IL-5 and IL-13 in AMPK KO/periodontitis mice further substantiates our working hypothesis that AMPK is a modulator/regulator of ILCs." (PMID 28861078, 2017).
ulcerative colitis (14 papers, 2015 to 2025). An inflammatory bowel disease involving the mucosal surface of the large intestine and rectum. "Previous data show that consumption of AbM extracts for 3 weeks reduced circulating IL-5 concentrations in patients with ulcerative colitis compared to baseline." (PMID 37432355, 2023). "In ulcerative colitis, IL-5 expression is increased and histological images show eosinophil infiltration, suggesting that IL-5 is involved in the pathogenesis of the disease." (PMID 39132061, 2022). "In contrast, patients suffering from ulcerative colitis, have a higher risk of CRC development and were found to have elevated IL-5 transcript levels." (PMID 32010138, 2019). "On the other hand, the IL-4 and IL-5 cytokines involved in ulcerative colitis are secreted by Th2 cells." (PMID 30254638, 2018). "Both the innate and adaptive immune systems are implicated in IBD pathogenesis, with CD being associated with Th1/Th17 responses, producing cytokines like IL-17, IFN-γ, and TNF-α, whereas ulcerative colitis features a Th2 response, with IL-5 and IL-13 activating B cells and NK T cells." (PMID 40507438, 2025). "In addition, patients with ulcerative colitis presented decreased levels of IL-2, IL-5 and MIP-1β after 21 days of consumption compared placebo group." (PMID 32714320, 2020). "There are several reports of increased GM-CSF in Crohn’s disease (CD) and ulcerative colitis (UC) patients, and concomitant Th17 and IL-5 and IL-13 T cell responses have been observed in ileal CD suggesting a more polyfunctional T cell response in certain patients." (PMID 26200014, 2015). "IL-5 and IL-13 correlate with TH2 polarization and TH2-mediated ulcerative colitis." (PMID 38395946, 2024).
chronic obstructive pulmonary disease (13 papers, 2015 to 2026). A chronic and progressive lung disorder characterized by the loss of elasticity of the bronchial tree and the air sacs, destruction of the air sacs wall, thickening of the bronchial wall, and mucous accumulation in the bronchial tree. "Results from the phase I clinical trials showed that Tozorakimab significantly reduced serum levels of pro-inflammatory cytokines, particularly IL-5 and IL-13, in patients with chronic obstructive pulmonary disease." (PMID 40764944, 2025). "One such disease state is allergic airway inflammation caused by type 2 (T2) cytokines (IL-4, IL-5, IL-13), which is common in both children and adults and has been associated with the development of both asthma and chronic obstructive pulmonary disease (COPD) in a subgroup of patients." (PMID 33046696, 2020). "Azithromycin decreases the secretion of IL-4, IL-5, IL-13, and IL-17A from peripheral blood mononuclear cells in patients with chronic obstructive pulmonary disease (COPD)." (PMID 37357527, 2023).
Insulin resistance (13 papers, 2016 to 2025). Increased resistance towards insulin, that is, diminished effectiveness of insulin in reducing blood glucose levels. "As with eosinophil deficiency, IL-5 deficiency in mice impairs eosinophil accumulation in AT, and mice develop increased body fat, impaired glucose tolerance and insulin resistance when fed a high fat diet." (PMID 35625566, 2022). "Cluster 5 showed a positive correlation of genes within IL-5 signaling and insulin resistance pathways." (PMID 40793786, 2025). "These cytokines are often associated with protective effects on the development of insulin resistance, as IL-13 production promotes an AAM phenotype and IL-5 is required for eosinophil recruitment and activation." (PMID 30755607, 2019). "TNF-α is a potent inducer of insulin resistance, whereas IL-5 can activate the eosinophil cells to participate in inflammation." (PMID 27738641, 2016). "In addition, IL-33 treatment of adipocytes and ATMs induces the production of IL-5, IL-6 and IL-13 which can exert protection against insulin resistance." (PMID 36994095, 2023).